TNF (tumor necrosis factor)
Diseases named in the same sentence as TNF in open-access papers (continued):
Sharing a sentence is not in itself a finding about the gene and the disease.
diarrhoea (15 papers, 2010 to 2025). "This change can lead to microbiota changes, increased intestinal permeability, and decreased absorptive function accompanying the overproduction of inflammatory cytokines such as IL-6, TNF-α, and IL-1β with ageing, thereby causing diarrhoea." (PMID 34946386, 2021). "Rotavirus infection was associated with increased TNFα levels in vitro and children suffering from rotavirus induced diarrhoea were characterized by significantly increased TNFα serum levels as compared to healthy controls." (PMID 30995806, 2019). "TNF-α has an effect on the activity of basolateral membrane, causing an increment of chloride (Cl−) secretion and decreases the absorption of natrium (Na+) in epithelial cells leading to accumulation of fluid in the small intestine that induced diarrhoea." (PMID 34367513, 2021). "Furthermore, the KEGG enrichment analysis revealed that the potential therapeutic pathways through which Lotus Leaf may exert effects in the treatment of porcine inflammatory diarrhea include the TNF signaling pathway and apoptosis signaling pathway." (PMID 40699713, 2025). "In addition, quercetin also significantly reduced diarrheal stools, the expression of IL-1β and TNF-α, and increased the NO level in an EPEC-induced diarrhea rat model." (PMID 39246650, 2024). "However, when the IBS group was split into subgroups of patients with IBS-C and IBS with diarrhoea (IBS-D), patients with IBS-D had the highest TNF-α and IL-6." (PMID 32443433, 2020). "Furthermore, FMT treatment resulted in up-regulation of another anti-inflammation cytokine (IL-4) and reduction of pro-inflammation cytokines, such as TNF-α and IFN-α, which are important mediators of the formation of colonic inflammation and diarrhoea in piglets." (PMID 32299514, 2020). "Moreover, the frequency of TNF-α and/or IFN-γ-producing VP6-specific CD4+ T cells was similar between children presenting with rotavirus-positive diarrhoea compared to rotavirus-negative diarrhoea." (PMID 37268634, 2023). "Furthermore, the frequency of CD69−IFN-γ+TNF-α+, CD69−IFN-γ−TNF-α+ and CD69−IFN-γ+TNF-α− CD4+ T cells were higher during acute infection compared to the convalescent stage in children with rotavirus-negative diarrhoea (p = 0.0102, p = 0.0157 and p = 0.0346, respectively)." (PMID 37268634, 2023).
familial Mediterranean fever (15 papers, 2013 to 2026). Familial Mediterranean fever (FMF) is an autoinflammatory disorder characterized by recurrent short episodes of fever and serositis resulting in pain in the abdomen, chest, joints and muscles. "Patient 1 is a developmentally normal 58-year-old male with a lifelong history of periodic fevers treated since childhood with colchicine and/or tumor necrosis factor alpha (TNF-α) inhibitors for a presumptive diagnosis of familial Mediterranean fever (FMF)." (PMID 41205602, 2025). "The first monogenetic defects linked to autoinflammation were described in 1999: familial Mediterranean fever (FMF) and tumor necrosis factor (TNF)-receptor-associated periodic syndrome (TRAPS)." (PMID 39618694, 2024). "In familial Mediterranean fever (FMF), ex vivo LPS-stimulated PBMCs and monocytes produce more IL-1α and β, IL-6, IL-8, IL-12, IL-18, and TNFα, and in non-stimulated PBMCs higher production of IL-6 and TNFα was found, and also expression of CD11b was increased." (PMID 29515591, 2018).
hip fracture (15 papers, 2013 to 2025). Traumatic or pathological injury to the hip in which the continuity of either the femoral head, femoral neck, intertrochanteric or subtrochanteric regions is broken. "Several studies have shown that 30-day mortality after a hip fracture is associated with elevated inflammatory cytokines, such as C-reactive protein, interleukin (IL)-6, IL-8, tumor necrosis factor-α, and soluble urokinase plasminogen activating receptor." (PMID 32850880, 2020). "In order to determine if hip fracture surgery was associated with changes in serum cytokine levels, IL-6, TNF-α, IL-1β, and IL-10 levels in blood were quantified 1, 3, and 7 days after hip fracture and surgery (including sham-operated controls)." (PMID 24163505, 2013). "The risk of hip fracture in women is related to the soluble receptors IL-1 and TNF-α." (PMID 40453580, 2025). "C-reaction protein, interleukin-6, and tumor necrosis factor-α are all inflammation biomarkers that have been shown to predict mortality events in hip fracture patients." (PMID 36628151, 2022). "Transversus abdominis plane block was postulated to attenuate the production of IL-6 in patients of advanced age undergoing laparoscopic rectal cancer surgery, and femoral nerve block reduced the expression of TNF-α in elderly patients with a hip fracture." (PMID 32756520, 2020). "Consistently, this study revealed that decrease of miR-130a-3p promotes the production of the pro-inflammatory factor TNF-α in hip fracture rats." (PMID 29357879, 2018). "Particularly, patients with hip fracture have significantly increased serum levels of inflammatory cytokines (e.g., TNF-α, IL-6, IL-10) compared with healthy controls." (PMID 29357879, 2018). "Dead or moribund rats with hip fracture exhibited significantly reduced TNF-α/IL-10 ratio compared with healthy controls and other hip fracture rats, which were therefore named as hip fracture rats with IMD." (PMID 29357879, 2018). "13.3% (6 of 45) of hip fracture rats were dead or became moribund at 72 h after hip fracture, and simultaneously, the serum TNF-α/IL-10 ratio in these rats was significantly downregulated compared with that in normal rats and other hip fracture rats." (PMID 29357879, 2018). "However, the alterations in cardiac glucose and fatty acid transporters following bone fracture were recently demonstrated to be induced by pro-inflammatory mediators such as HMGB1, IL-1β, IL-6 and TNF, all of which have been shown to be elevated following hip fracture in the present study." (PMID 36131923, 2022). "However, the regression model within the hip fracture patients were not significant for the association between depressive symptoms and TNFα, β = .19, p = .24, ΔR2 = .034." (PMID 23876747, 2013). "On examining cytokine production by activated T cells, a significant increase in TNFα (p = .03) and IL6 (p = .04) production was observed in CD4 T cells from hip fracture patients with depressive symptoms compared to healthy controls." (PMID 25628751, 2014). "We have previously reported that elevated levels of TNFα and IL6 were seen in hip fracture patients with depressive symptoms compared with patients without depressive symptoms and healthy controls." (PMID 25628751, 2014). "In this study, we have reported elevated levels of TNFα and IL6 in hip fracture patients with depressive symptoms compared with patients without depressive symptoms and healthy controls." (PMID 23876747, 2013). "Specifically, the hip fracture patients presented significant negative correlations between the pro-inflammatory marker tumor necrosis alpha (TNF-α) and two SCFAs, namely propionate (ρ=-0.47, p-value = 0.007) and valerate (ρ=-0.39, p-value = 0.03)." (PMID 37526398, 2023). "However, TNFα, and IL1β did not correlate with depressive symptoms in the present study, nor did the hip fracture patient groups differ on these cytokines, other than for TNFα." (PMID 23876747, 2013).
hip fracture (continued). "These symptoms were associated with poorer neutrophil superoxide production and a higher cortisol:DHEAS ratio, as well as greater levels of the cytokines IL6 and TNFα and lower IL10, compared to healthy controls and hip fracture patients without depressive symptoms." (PMID 23876747, 2013).
Hypercalcemia (15 papers, 2012 to 2026). An abnormally increased calcium concentration in the blood. "Cytokine-mediated hypercalcemia (~60%), primarily driven by IL-6, RANKL, MIP-1α, and TNF-α, was most frequent, followed by PTHrP-mediated hypercalcemia (~25%) and less commonly by 1,25-dihydroxyvitamin D dysregulation (~15%)." (PMID 40438858, 2025). "TNF-α, IL-1β, vitamin D and PTHrP are potent calciotropic factors able to increases bone resorption and serum hypercalcemia." (PMID 29670736, 2018). "In one series of 21 patients, 11 had PTHrP-mediated hypercalcaemia, while two patients had raised TNF-α and IL-6." (PMID 26082799, 2015). "Three of them were considered to develop humoral hypercalcemia (high PTHrP level), whereas one patient resembling normal PTHrP was believed to have hypercalcemia related with tumor synthesis of osteoclast-activating factors [interleukin (IL)-1, IL-6, tumor necrosis factor-α, and prostaglandins]." (PMID 28443817, 2017). "The proposed mechanism of hypercalcemia was upregulation of tumor-produced PTHrP and TNF-α." (PMID 29056680, 2017). "Stimulated by IFN-γ, tumour necrosis factor-α (TNF-α, IL1 and IL2), macrophages from sarcoid granulomas, can spontaneously release 1,25-dihydroxy vitamin D, further boosting calcium resorption from the gastrointestinal tract and bone, and causing hypercalcemia and hypercalciuria." (PMID 34947932, 2021). "Hypercalcemia, observed in 80% of cases, was primarily cytokine-driven, involving IL-6, RANKL, MIP-1α, and TNF-α." (PMID 40438858, 2025). "Constitutive overexpression and secretion of TNF-α by Chinese hamster ovarian cells resulted in increased osteoclastic bone resorption and HHM in mice, whereas bone resorption or hypercalcemia did not occur with control cells." (PMID 29056680, 2017).
intracranial hemorrhage (15 papers, 2013 to 2025). Bleeding within the SKULL, including hemorrhages in the brain and the three membranes of MENINGES. "It is known that the risk for intracranial hemorrhage (ICH) in AVM is linked to polymorphisms in the inflammatory cytokine genes such as TNF-α and IL-6." (PMID 33648532, 2021). "TLR4, TNF and NLR deficiency significantly attenuated ischemic brain injury, brain hemorrhage and hemorrhagic transformation to some extent by decreasing the inflammatory response in the brain." (PMID 36755018, 2023). "Within 4 hours after intracranial hemorrhage, neutrophil infiltration occurred around the hematoma, and the expression of IL-1β, TNF-α and pro-inflammatory protease increases significantly." (PMID 34511434, 2021). "Following brain hemorrhage, resident immune cells are activated and release proinflammatory cytokines and chemokines, such as tumor necrosis factor-α (TNF-α) and interleukin 6 (IL-6), inducing endothelial cells to upregulate intercellular adhesion molecule (ICAM-1)." (PMID 37899442, 2023). "The cause of dyshomeostasis in brain function may be, for example, brain hemorrhage due to trauma, which exacerbates astrogliosis and increases proinflammatory cytokines tumor necrosis factor- α (TNF-α) and interleukin-1β." (PMID 37371389, 2023). "This research introduces an innovative and functional nomogram that utilizes the NLR, age of 65 years or older, TNF-α, and D-Dimer concentrations to accurately forecast the likelihood of developing postoperative UTI following intracranial hemorrhage." (PMID 41357523, 2025). "For example, in intracranial hemorrhage, free heme induces microglial activation via TLR4 and the MyD88/TRIF signaling pathway, resulting in the increased expression of TNF." (PMID 31358003, 2019). "Another study also reported that UTI could attenuate the brain edema after intracranial hemorrhage (ICH) of male Sprague-Dawley rats and that the preliminary molecular mechanism may be related to the decrease of the expression levels of proinflammatory cytokines including IL-1β and TNF-α." (PMID 36545238, 2022).
lupus erythematosus (15 papers, 2012 to 2025). An autoimmune, connective tissue chronic inflammatory disorder affecting the skin, joints, kidneys, lungs, heart, and the peripheral blood cells. "Due to this and the possibility of increased risk of infection, drug-induced Lupus Erythematosus, and possible increased risk of cancer, many healthcare professionals avoid using anti-TNF-α therapies as treatment for SLE." (PMID 40650157, 2025). "However, exposure to anti-TNF-α therapeutics can lead to drug-induced lupus erythematosus (DILE), which may rarely be accompanied by cardiac manifestations." (PMID 37090269, 2023). "In lupus erythematosus, IFNs, particularly IFN-κ and IFN-α, amplify inflammatory cascades in the skin characterized by cytokines such as IL-6, IL-1β, and TNF-α, and chemokines (CXCL9, CXCL10), resulting in sustained immune cell infiltration." (PMID 41479908, 2025). "Discoid lupus erythematosus (DLE) was significantly separated from control skin by all of the signatures (p < .05); IFNB1 had the greatest size (Hedge’s g = 12.4) followed by IFNW1 (g = 9.7), IFNG (g = 8.7), IFNA2 (g = 7.9), IL12 (g = 5.2), and TNF (g = 2.8)." (PMID 31044165, 2019).
oral diseases (15 papers, 2020 to 2025). "Several types of inflammatory biomarkers associated with both oral diseases and inflammatory disease have been identified in adult saliva, for example, interleukins (IL-1, IL-6, and IL-8), tumor necrosis factor (TNF), and matrix metalloproteinases (MMP)-8 and MMP-9." (PMID 32344523, 2020). "With biomarkers like IL-1β, IL-6 and TNF-α helpful in determining theinflammatory status in oral disorders, the dynamic nature of saliva permits immediate tracking of progressing illness and therapyresponses." (PMID 40230914, 2024). "Both TNF-α and IL-1β are also considered to be possible indicators of malignant transformation in oral disorders." (PMID 34064411, 2021). "Interleukins (IL-1, IL-6, and IL-8), tumor necrosis factor (TNFα), matrix metalloproteinases (MMP-8 and MMP-9), and tissue inhibitors of metalloproteinase are the most significant salivary inflammatory indicators associated with oral diseases." (PMID 38535279, 2024). "The most important salivary inflammatory biomarkers linked to oral disorders include matrix metalloproteinases (MMP-8 and MMP-9), tissue inhibitors of metalloproteinase, interleukins (IL-1, IL-6, and IL-8), and tumor necrosis factor (TNF-α)." (PMID 38535833, 2024). "In oral diseases, GA plays an antibacterial role in changing the morphology and structure of dental plaque biofilm, reducing the density of biofilm and killing bacteria in biofilm, and inhibiting the secretion of TNF-α." (PMID 36143428, 2022). "TNF-α has been observed in a participant role in OSCC but additionally in pre-malignant mucosal and microbiome-related oral disease, complicating its allocation to a biomarker role." (PMID 36980727, 2023). "The broad and multifaceted role that TNF-α plays in many inflammatory conditions presents an obvious confounder, particularly with demonstrated increased TNF-α levels in common oral disease states." (PMID 36980727, 2023). "The broad and multifaceted role that TNF-α plays in many inflammatory states presents an obvious confounder, particularly with demonstrated increased TNF-α levels in common oral disease states." (PMID 36980727, 2023). "Compared with the oral disease group, the HLJDD intervention group showed significantly reduced levels of TNF-α (p < 0.01) and IL-8 (p < 0.05)." (PMID 33995016, 2021).
pericarditis (15 papers, 2012 to 2026). An inflammatory process affecting the pericardium. "It has been suggested that the cause is failure of anti-TNFα therapy to control the extra-articular manifestations of RA, of which pericarditis is common." (PMID 27822400, 2016). "Herein, we present a case of pericarditis induced by tumor necrosis factor-alpha antagonist, adalimumab." (PMID 36874325, 2023). "Pericarditis is a rare but serious complication of anti-TNF based therapy, and hemorrhagic fluid is even more rare, with only one additional case reported." (PMID 27822400, 2016). "In the atorvastatin and pericarditis groups, the serum levels of IL-6 and TNF-α were significantly increased 12 h after surgery (P<0.05), peaked 48 h after surgery and were significantly higher compared with the levels in the control group (P<0.05)." (PMID 25524260, 2015). "In the atorvastatin and pericarditis groups, serum levels of IL-6 and TNF-α gradually decreased, but remained higher than at the preoperative stage, even following the 21 day endpoint (P<0.05)." (PMID 25524260, 2015). "The levels of high-sensitivity C-reactive protein (hs-CRP), interleukin(IL)-6 and tumor necrosis factor-α (TNF-α) were significantly elevated following surgery in the untreated pericarditis and atorvastatin groups compared with the control group (P<0.05)." (PMID 25524260, 2015). "However, lower levels of hs-CRP, IL-6 and TNF-α were observed in the atorvastatin group compared with the untreated pericarditis group (P<0.05)." (PMID 25524260, 2015). "Although still rare, most patients with pericardial effusion during anti-TNFα therapy have RA or DILE whereas ours is only the third reported case of pericarditis without evidence of RA or DILE." (PMID 27822400, 2016). "Literature regarding the use of biologic Disease Modifying Antirheumatic Drugs (DMARDs) for BS-related pericarditis is scarce: in refractory cases, anti-IL1 agents may be considered, while no data exist on anti-Tumor Necrosis Factor (TNF) agents." (PMID 40676431, 2025).
proliferative diabetic retinopathy (15 papers, 2010 to 2025). Advanced retinopathy due to diabetes mellitus characterized by the formation of new vessels in the retina. "Another study showed that patients with proliferative diabetic retinopathy had significantly higher serum TNFα levels compared with those with a milder form of retinopathy." (PMID 24905410, 2014). "In patients with proliferative diabetic retinopathy, there is a high concentration of interleukin-1 (IL-1), which activates the lymphocytes, IL-8 (with chemotactic role on neutrophils), IL-18 (activates macrophages) and tumor necrosis factor alpha (TNF alpha)." (PMID 35087972, 2021). "TNF-α has previously been shown to be increased in blood serum from mice subjected to ischemia-reperfusion and in vitreous and blood serum from patients with proliferative diabetic retinopathy." (PMID 21152396, 2010). "Among those cytokines, the frequently reported cytokines such as TNF-α, IL-6, and TGF-β were compared between our study and proliferative diabetic retinopathy, and the expressions of the three cytokines in proliferative diabetic retinopathy were found times higher as compared with those in MH/ERM." (PMID 34336263, 2021).